CMTR1 (cap methyltransferase 1)
Description:
S-adenosyl-L-methionine-dependent methyltransferase that mediates mRNA cap1 2'-O-ribose methylation to the 5'-cap structure of mRNAs. Methylates the ribose of the first nucleotide of a m(7)GpppG-capped mRNA and small nuclear RNA (snRNA) to produce m(7)GpppRm (cap1). Displays a preference for cap0 transcripts. Cap1 modification is linked to higher levels of translation. May be involved in the interferon response pathway.
Synonyms: MTr1; hMTr1; ISG95; FTSJD2; KIAA0082
Tractability: Small molecule: a structure with a bound ligand is known. PROTAC: ubiquitination databases record sites on it; its protein half-life has been measured.
Gene: Protein-coding gene on chromosome 6 (37,433,094 to 37,482,827, forward strand). Ensembl gene ENSG00000137200.
Subcellular location: Nucleus
Subcellular location (Human Protein Atlas): Nucleoplasm; Vesicles
Gene Ontology:
Molecular function: methyltransferase cap1 activity; methyltransferase activity; nucleic acid binding; O-methyltransferase activity; RNA methyltransferase activity
Biological process: 7-methylguanosine mRNA capping; mRNA processing
Cellular component: nucleoplasm; nucleus; cytoplasm
Genetic constraint (gnomAD): Loss-of-function variants: 31 observed, 95.66 expected, observed/expected ratio (o/e) 0.32, 90% interval 0.24 to 0.44. The upper end of that interval is the gene's LOEUF score, 0.44, which puts it in group 1 of 6, group 1 being the genes least tolerant of losing a copy. Missense variants: 614 observed, 1,024.6 expected, observed/expected ratio (o/e) 0.6, 90% interval 0.56 to 0.64. Synonymous variants: 346 observed, 371.55 expected, observed/expected ratio (o/e) 0.93, 90% interval 0.85 to 1.02.
Homologues: Orthologues: chimpanzee CMTR1 (100% identical), macaque CMTR1 (99% identical), pig CMTR1 (96% identical), dog CMTR1 (94% identical), guinea pig CMTR1 (90% identical), mouse Cmtr1 (90% identical), rabbit CMTR1 (88% identical), rat Cmtr1 (88% identical), tropical clawed frog cmtr1 (75% identical), zebrafish cmtr1 (71% identical), Drosophila melanogaster Cmtr1 (37% identical), Caenorhabditis elegans cmtr-1 (36% identical). Paralogues in human: CMTR2 (15% identical).